CRP (C-reactive protein)
Diseases named in the same sentence as CRP in open-access papers (continued):
Sharing a sentence is not in itself a finding about the gene and the disease.
Hypoalbuminemia (continued). "Hypoalbuminemia, inflammatory status (C-reactive protein >10 mg/dL or interleukin-6 ≥10 pg/mL), and female gender were associated with increased, while age ≥85 years with decreased risk of seropositivity." (PMID 36361095, 2022). "The risk increased with hypoalbuminemia, higher serum CRP level (as well as CPR > 3 mg/dL) or plasma IL-6 level (as well as IL-6 ≥ 10 pg/mL), inflammatory status (CRP > 10 mg/dL or IL-6 ≥ 10 pg/mL), and female gender." (PMID 36361095, 2022). "Univariate analysis revealed that decreased LVEF, higher TAVR score, higher serum CRP level, hypoalbuminemia, higher CAR value and postprocedural acute kidney injury were also associated with late mortality." (PMID 35244369, 2022). "In a subset of dogs, serum hypoalbuminemia (116/662, 17.5%), hypocobalaminemia (98/647, 15.1%), and increased C-reactive protein (CRP) concentrations (145/267, 54.3%) were diagnosed." (PMID 35739843, 2022). "Laboratory markers that lead to systemic inflammatory responses, such as CRP, hypoalbuminemia, white blood cell count, neutrophil/lymphocyte ratio (NLR), or platelet/lymphocyte ratio, have been shown to be prognostic and predictive factors for several tumors." (PMID 35832647, 2022). "Patients with elevated CRP levels > 10 mg/L and normal albumin are classified as mGPS-1, and patients with elevated CRP and hypoalbuminaemia (< 35 g/L), are classified as mGPS-216." (PMID 35739171, 2022). "Moderate pancytopenia, hypoalbuminemia, and increased CRP and D-dimer were also observed in blood tests." (PMID 36118327, 2022). "A poor cancer prognosis is determined by changes in acute-phase proteins (elevated CRP and hypoalbuminemia) and white blood cell counts (elevated neutrophil count and low lymphocyte count) of the systemic inflammatory response." (PMID 35866083, 2022). "Laboratory findings included an elevated C-reactive protein (CRP) and sedimentation rate, hypoosmolar hyponatremia, hypoproteinemia, and hypoalbuminemia." (PMID 36570116, 2022). "Of the 88 patients, 83 (94%) had positive CRP values (>5 mg/L), 17 (19%) had hemoglobin values <10 g/dL, and 27 (31%) had hypoalbuminemia (albumin <3 g/dL) upon hospital admission." (PMID 34830694, 2021). "We compared inpatients and outpatients and investigated factors potentially associated with QF usefulness (steroid exposure, C-reactive protein (CRP), hypoalbuminaemia, thrombophilia)." (PMID 33919426, 2021). "The findings of this study indicate that variability of voriconazole remains high despite the 2012 updated dosing recommendations, and that drug levels are influenced by severe hypoalbuminemia and elevated C-reactive protein (CRP)." (PMID 34200506, 2021). "Elevated biomarkers, such as white cell count, neutrophil count, C-reactive protein (CRP), urea, creatinine, transaminases, cardiac troponin I, and D-dimer, as well as low lymphocyte count and hypoalbuminemia, are associated with excess in-hospital mortality." (PMID 33624101, 2021). "The combination of higher CRP and hypoalbuminemia can be also a sensitive biomarker for cancer-related prognosis." (PMID 34360768, 2021). "Laboratory evaluation revealed elevated CRP of 6.73 mg/dl, hypoalbuminemia of 2.6 g/dl (normal 3.5–5.20 g/dl), moderate eosinophilia of 1800/mm3, with normal immunoglobulin levels." (PMID 33787639, 2021). "Namely, high GPS reflects both systemic inflammation (elevated CRP) and low nutritional state (hypoalbuminemia)." (PMID 34360768, 2021). "Systemic inflammatory response (SIR) markers, such as Serum C-reactive protein (CRP), hypoalbuminemia, absolute white blood cell count (WBC), and their components have been shown to play essential roles in the development and progression of cancer." (PMID 35198586, 2021). "Urine analysis detected high levels in nephrotic range (1873 mg 24 h) and blood tests showed hypoalbuminaemia (1.1 g/dL), hyperlipidaemia (cholesterol 333 mg/dL), hyperfibrinogenemia (1394 mg/dL) and high C-reactive protein (CRP 7.5 mg/dL)." (PMID 32720138, 2021).
Hypoalbuminemia (continued). "Numerous studies have examined the risk factors for hospitalization of patients with COVID‐19, including high CRP, old age, low lymphocyte count, elevated cytokine levels, and hypoalbuminemia." (PMID 34534417, 2021). "It indicated that exploring hypoalbuminemia and high CRP levels in the elderly has greater significance and more attention should be paid to the treatment of hypoalbuminemia and high CRP levels in the elderly in subsequent studies." (PMID 34961476, 2021). "Other important findings include elevated CRP (98/112, 87.5%), high ferritin level (21/22, 95.5%) and hypoalbuminemia (44/88, 50%)." (PMID 34776007, 2021). "Compared with the control group, the study group revealed significant hypoalbuminemia (p = 0.011) and higher preoperative C-reactive protein (CRP) (p = 0.001) and platelet (p = 0.048) levels." (PMID 34830626, 2021). "In this patient, hypoalbuminemia, decreased C3, increased CRP, and high SLEDAI implied an increase in lupus activity, but the significant association between these findings and the occurrence of severe hyponatremia was inconclusive." (PMID 34596163, 2021). "Prednisone was initiated at a dose of 60 mg daily, with rapid resolution of peripheral eosinophilia and hypoalbuminemia and decrease in CRP to normal levels." (PMID 33787639, 2021). "Second, patients with ILD of a known etiology were excluded from this study because these diseases affect elevated CRP and/or hypoalbuminemia." (PMID 33480111, 2021). "HHV8-positive MCD shows systemic symptoms, multiple lymphadenopathy, cytopenia, splenomegaly, hypoalbuminemia, hypergammaglobulinemia, elevated serum levels of inflammatory markers such as C-reactive protein and interleukin 6 (IL-6)." (PMID 33906629, 2021). "Our study indicated that a high hs-CRP level increases the risk of long-term all-cause mortality, especially in CAD patients with hypoalbuminemia." (PMID 34961476, 2021). "The results of that study were similar to ours, in which age, low physical activity, high C-reactive protein level, and hypoalbuminemia—all of which are known predictors for mortality in hemodialysis patients—predicted all-cause mortality in our patients." (PMID 34513029, 2021). "The role of hypoalbuminemia and raised C-reactive protein (CRP) levels in predicting critical prognosis has been described extensively in adult literature." (PMID 33779823, 2021). "The present study aimed to evaluate the independent and joint effects of high hs-CRP levels and hypoalbuminemia on long-term mortality among CAD patients." (PMID 34961476, 2021). "Upon admission, our patient presented with hyponatremic encephalopathy, increased levels of CRP and erythrocyte sedimentation rate, and hypoalbuminemia." (PMID 34596163, 2021). "The incidences of reduced lymphocytes, thrombocytopenia, hypoalbuminemia, elevated C-reactive protein, ferritin, LDH, interleukin-6, PCT, and FIB were 61.51%, 26.42%, 77.92%, 98.5%, 86.79%, 80.59%, 89.30%, 85.10%, and 87.01%, respectively." (PMID 34336288, 2021). "As a result of higher CRP concentrations and hypoalbuminemia, significantly more patients with lung cancer than subjects from the control group had a high Glasgow prognostic score (GPS)." (PMID 34832849, 2021). "Therefore, the current study aimed to test whether high hs-CRP levels can, independently and jointly with hypoalbuminemia, predict an increased risk of all-cause mortality among CAD patients in a multicenter prospective Reduction of Risk for Contrast-Induced Nephropathy (REICIN) study." (PMID 34961476, 2021). "With the increasing numbers of studies about GPS and survival in patients with cancers, researchers found that hypoalbuminemia regularly occurred with elevated CRP levels." (PMID 34221991, 2021). "Studies have shown a positive correlation of NT-pro-BNP with C-reactive protein and hypoalbuminemia in children with KD during initial phase of disease." (PMID 33072669, 2020).
Hypoalbuminemia (continued). "These include two clinical scoring systems, hypocobalaminemia, hypoalbuminemia, serum C-reactive protein (CRP), and a high canine pancreatic lipase immunoreactivity concentration." (PMID 32971945, 2020). "The traditional GPS is derived by allocating one point each for elevated CRP (>10 mg/L) and hypoalbuminemia (serum albumin < 35 g/L), so that patients with both, one, or none of these conditions would have a score of 2, 1, or 0, respectively." (PMID 31998420, 2020). "These factors include older age, cardiovascular diseases, acute kidney injury, high Sequential Organ Failure Assessment (SOFA) score, hypoalbuminemia, and elevated levels of transaminase, lactate dehydrogenase, ferritin, D-dimer, and C-reactive protein." (PMID 33224529, 2020). "Analysis of the biomarkers showed that about one-fifth of older adults with SO also had hypoalbuminemia, about one-third had hyperglycemia, and about one-quarter had elevated CRP levels." (PMID 33263630, 2020). "Regarding hypoalbuminemia and high serum CRP levels, recent studies revealed that these characteristics are associated with immunosuppression and malnutrition in cancer patients." (PMID 33005853, 2020). "That is, although hypoalbuminemia is more likely to occur secondary to elevated CRP levels, a crucial difference between the GPS and mGPS is the inclusion of patients with hypoalbuminemia in the absence of elevated CRP levels." (PMID 33227100, 2020). "Markers of severe disease in COVID-19 include lymphopenia, leukocytosis, hypoalbuminemia as well as elevated levels of alanine transaminase, C-reactive protein, ferritin, lactate dehydrogenase, and D-dimer." (PMID 33224529, 2020). "Even before this 2-week period, mean CRP levels were above 100 mg/L, indicating an ongoing inflammation, and mean PA levels were ~ 30 g/L (i.e. hypoalbuminemia)." (PMID 32209087, 2020). "It is worth noting that NLR is one of the many potential inflammatory prognostic biomarkers, which include C-reactive protein, hypoalbuminemia, elevated LDH, and platelet-to-lymphocyte ratio." (PMID 33622996, 2020). "The inflammatory cytokines also induce a reduction of serum albumin as CRP production is prioritized, and the kinetics promote exacerbated hypoalbuminemia when patients fail to intake required nutrition in disorders such as cachexia." (PMID 32567660, 2020). "Hypoalbuminemia often occurs secondary to systemic inflammatory responses and is observed together with increasing CRP in patients with various types of cancer." (PMID 32441463, 2020). "Considering both the low rate of pathologically elevated plasma CRP concentrations and the low incidence of hypoalbuminemia, the distribution of the GPS was thus shifted towards a score of 0 in the vast majority of the cases." (PMID 31936329, 2020). "Upon admission, high C‐reactive protein (CRP) level was recorded in 79% cases, hypoalbuminemia in 10%." (PMID 32514454, 2020). "Elevated β2MG positively correlated with hypoalbuminemia and high CRP levels, but negatively correlated with use of statins and high eGFR at the start of hemodialysis." (PMID 33019590, 2020). "The CRP/PNI ratio was associated with CRP (p<0.001), PNI (p<0.001), platelet count (p=0.049), hypoalbuminemia (p=0.032), lymphocyte count (p=0.046), and survival (p=0.010)." (PMID 31312573, 2019). "Multivariate Cox proportional hazard analysis adjusted for old age, DM, history of cardiovascular disease, hypoalbuminemia, hs-CRP level, and the presence of baseline AAC determined that AAC progression was significantly associated with inferior survival." (PMID 31048884, 2019). "The rate of hypoalbuminemia and a high hs-CRP level in patients with any 1 marker was 81.4% and 18.6%, respectively." (PMID 31048884, 2019). "An elevation of serum neutrophils, CRP, total bilirubin, as well as a lower platelet count, hyponatremia, and hypoalbuminemia are commonly observed in KD patients, which is similar to our findings." (PMID 31533770, 2019).
Hypoalbuminemia (continued). "In the end, these same patients had hypozincemia, and two of them had hypoalbuminemia and a high CRP as well." (PMID 31694220, 2019). "He presented hepatosplenomegaly, gallbladder hydrops, neutrophil leucocytosis, hyponatraemia (128 mEq/l), hypoalbuminemia, significant increase of C-reactive protein (CRP) 13 mg/dl; erythrocyte sedimentation rate (ESR): 57; D-dimer." (PMID 31627741, 2019). "Hypoalbuminemia (Odds ratio 3.296; 95% confidence interval 1.178–9.222), hs-CRP (1.561; 1.038–2.348), low LDL-cholesterol (0.976; 0.955–0.996), and the presence of baseline AAC (10.136; 3.173–32.386) were significant risk factors for AAC progression." (PMID 31048884, 2019). "Initially, hypoalbuminemia was observed in 50% of patients, high levels of CRP in46.6%, and high levels of total cholesterol, LDL and triglycerides of 37.5%,66.6% and 75% respectively." (PMID 31419271, 2019). "In univariate analysis, hypoalbuminemia, hs-CRP, low LDL-cholesterol, iPTH, and the presence of baseline AAC were significantly associated with AAC progression." (PMID 31048884, 2019). "In both groups of ZS, there was a small but positive and significant change in body mass and normalization in BMI Z-score, hypoalbuminemia, hypozincemia and high CRP, especially with 30 mg/day of ZS." (PMID 31694220, 2019). "Since both systemic inflammation and malnutrition contribute to worse survival outcomes in malignancy, the GPS, which incorporates elevation of CRP levels and hypoalbuminemia, is a possible independent prognostic indicator for worse prognosis." (PMID 31547247, 2019). "Even though there was an increase in patients with elevated CRP (from 40% to 54.5%), with hypoalbuminemia (from 36.8% to 37.5%) and with hypozincemia (from 40.5% to 41.7%), these changes were not significant." (PMID 31694220, 2019). "Our findings indicate that age < 65 years, hypoalbuminemia, need for IVRS, and high serum CRP levels on admission are independent risk factors for the development of bacteremia in patients with pneumococcal CAP." (PMID 29382316, 2018). "We also showed that low LMR was associated with metastasis (lymph node and bone metastasis), malnutrition (hypoalbuminemia) and increased CRP." (PMID 30192878, 2018). "Age < 65 years, hypoalbuminemia, IRVS, and high C-reactive protein level on admission are independent risk factors for the development of bacteremia in patients with community-acquired pneumococcal pneumonia." (PMID 29382316, 2018). "There was a significant relation between LMR and GPS, and LMR was significantly decreased in patients with hypoalbuminemia or increased CRP." (PMID 30192878, 2018). "The prognostic value of the combination of an elevated CRP concentration and hypoalbuminaemia was verified in many cancers including colorectal cancer." (PMID 30627541, 2018). "Admission blood work revealed a normal complete blood count, slightly elevated serum transaminase levels, mild hypoalbuminemia (30 g/L), and a normal c-reactive protein (CRP) of 2.6 mg/L." (PMID 29970110, 2018). "Several researches have revealed that the occurrence of decreased serum ALB levels, namely hypoalbuminemia, is secondary to the elevation of serum CRP, as many cancer patients with hypoalbuminemia already have high concentrations of serum CRP." (PMID 29568406, 2018). "One ERAS patient placed abdominal drains because of hypoalbuminemia and higher C-reactive protein level; another patient placed abdominal drains due to damage of the hepatic flexure during the operation." (PMID 30534152, 2018). "Several studies have suggested that the progression of hypoalbuminemia is secondary to the serum elevation of CRP, as many cancer patients with hypoalbuminemia already have increased serum CRP levels." (PMID 28431566, 2017). "By univariate analysis, we have shown that tumor stage, postoperative residual tumor, histological subtype, ascites, CRP, hypoalbuminemia and age, as well as CRP/Alb, GPS, mGPS, PLR, PNI and PI, are predictors of OS in ovarian cancer." (PMID 28431566, 2017).
Hypoalbuminemia (continued). "This cytokine is associated with some laboratory findings such as the hypercoagulability, hypoalbuminemia and C-reactive protein (CRP)." (PMID 28594861, 2017). "A total of 110 (55%) patients had an elevated CRP concentration (10 mg/L), and 22 (11%) patients had hypoalbuminemia (albumin <35 g/L) prior to surgery." (PMID 28431566, 2017). "Several studies have found that the deterioration of hypoalbuminemia is secondary to the elevation of serum CRP, as many cancer patients with hypoalbuminemia already have increased serum CRP levels." (PMID 29137238, 2017). "The CRP level was considered high if it exceeded 10 mg/L, and hypoalbuminemia was defined as a level lower than 35 g/L." (PMID 27873100, 2017). "Preoperative elevated CRP was found in 54 (19.4%) patients and hypoalbuminemia in 32 (11.4%) patients." (PMID 28740506, 2017). "Measurable parameters in the blood suggest a systemic inflammatory response including: elevated CRP, IL-6 and other pro-inflammatory cytokines, hypoalbuminaemia, leucocytosis and neutrophilia." (PMID 28384249, 2017). "Patients with life-threatening conditions were generally biochemically abnormal, with hypoalbuminemia, acidosis and a raised CRP." (PMID 29261657, 2017). "The results of our meta-analysis are in accordance with these reports, in which n-3 PUFAs reduced host inflammatory response by decreasing the concentration of IL-6, TNF-α, and CRP, and improving hypoalbuminemia." (PMID 28410575, 2017). "Patients with TAFRO-iMCD and iMCD-NOS commonly demonstrated microcytic anemia, hypoalbuminemia, and elevated serum CRP." (PMID 28205564, 2017). "The Glasgow prognostic score, a combined score based on hypoalbuminemia and the C-reactive protein level, is an established predictor of survival after surgery." (PMID 28836976, 2017). "The results of the present study have shown that CRP elevation and hypoalbuminemia decreased voriconazole clearance and that concomitant glucocorticoid administration increased voriconazole clearance." (PMID 27096102, 2016). "Patients with GPS more than zero have elevated CRP or hypoalbuminaemia or even both of them, implying GPS presents not only inflammation status but also nutritional status of cancer patients." (PMID 28008988, 2016). "Although preoperative GPS was significantly predictive of OS (P = 0.033), high CRP levels (>10 mg/L) and hypoalbuminemia (<35 g/L) were observed in only 39 (15.0%) and 2 (0.8%) of 260 ESCC patients, respectively." (PMID 26754834, 2016). "CRP and albumin were the acute phase proteins measured since both markers constitute the Glasgow prognostic score, which is a cumulative score based on elevated CRP and hypoalbuminemia." (PMID 26808421, 2016). "In acute severe colitis or fulminating colitis, elevated CRP, thrombocytosis and hypoalbuminemia (<3.5 g/dl) can be found." (PMID 27759787, 2016). "We propose that early measurement of voriconazole concentration before the plateau phase will lead to avoidance of a toxic voriconazole level in patients with elevated CRP level and hypoalbuminemia, although further studies are needed to confirm our findings." (PMID 27096102, 2016). "Present study showed that hypoalbuminemia as well as increased CRP and ferritin were significantly more common in deceased in comparison to survived AKI patients." (PMID 27471736, 2016). "mGPS (a compound variable of CRP and hypoalbuminemia) and NLR score (a systemic inflammation-based scoring system) have been shown to be of prognostic significance in different cancers including SCLC." (PMID 27537502, 2016). "The AUC of CRP in the preoperative period to the development of hypoalbuminemia on POD 3 was 0.579 (95 % CI 0.392–0.766) with an optimal threshold of 0.86 mg/dL, sensitivity of 36.4 % and specificity of 93.3 %, and the diagnostic accuracy resulted as failed." (PMID 26530188, 2015).